CKB (creatine kinase B)
Diseases named in the same sentence as CKB in open-access papers (continued):
Sharing a sentence is not in itself a finding about the gene and the disease.
tumor (39 papers, 1996 to 2026). "Despite minimal changes in proliferation in vitro in response to the loss of CKB, there was a robust decrease in the PyMT Ckb KD tumor growth rate." (PMID 35008190, 2021). "HIF-1 loss, and thus, reduced CKB, is targeted only to the tumor epithelium; therefore, a significant proportion of the CKB signal observed in whole tumor extracts is likely derived from the stroma." (PMID 35008190, 2021). "It is possible that the loss of epithelial-derived CKB disrupts a paracrine network necessary to promote tumor growth." (PMID 35008190, 2021). "Although reduced CKB expression was associated with a poor prognosis and late-onset GC, reduced CKB methylation was associated with advanced stage, deeper tumor invasion, lymph node or distant metastasis and with late-onset GC." (PMID 26460485, 2015). "Reduced percentage of SRC, LYN and CKB methylation were associated with advanced stage, deeper tumor invasion, and the presence of lymph node and distant metastases (p < 0.05, for all comparisons)." (PMID 26460485, 2015). "Increased protein and mRNA expression of SRC and LYN and reduced CKB expression were associated with advanced stage, deeper tumor invasion, and the presence of lymph node and distant metastases (p < 0.05, for all comparisons)." (PMID 26460485, 2015). "Given that CKB is suggested to be critical for epithelial integrity, downregulation of CKB may be a part of general mechanisms underlying epithelial cell's loss of their polarity and integrity during the process of tumor transformation." (PMID 34706306, 2021). "Protein profiling identified ITH-associated proteins (WDR5, CKB, IPO11, ATP6V1F, DCXR and PCCB) and underscored pathway variations including tumour suppressor and proto-oncogenic signalling, vascularization and metabolic regulation." (PMID 41580526, 2026). "Conversely, gene expressions previously linked to tumor cell differentiation and favorable outcome, such as SLC26A3, PIGR, CKB and FABP1, were highly expressed in GPA33-high cancer cells." (PMID 39472498, 2025). "The ZEB1-KAT2B complex promotes CKB (CK, brain-type) expression, increasing PCr levels in GSCs compared to differentiated tumor cells, emphasizing metabolic heterogeneity within GBM." (PMID 40565099, 2025). "Our data show that CKB silencing increases anoikis sensitivity in H1299 cells, leading to enhanced cell death in suspension cultures, a condition that mimics circulating tumor cells in vivo." (PMID 41072771, 2025). "Our results demonstrate that CKB silencing reduces tumor progression by limiting metastasis to the lungs and liver, highlighting CKB as a potential therapeutic target for NSCLC metastatic lung cancer." (PMID 41072771, 2025). "The link of CKB to mTORC1 signaling also suggests its involvement in metabolic regulation and growth signaling, essential for tumor survival." (PMID 40600620, 2025). "For example, creatine kinase-B (CKB) has been identified as a cancer driver in KRAS-mutant CRC by promoting tumor growth and survival in hypoxia." (PMID 40361439, 2025). "Compared with normal mucosa, 184 CRC tissues had higher levels of CKB and MTCK, and these levels were associated with histological grade, tumor invasion, and distant metastasis." (PMID 37204253, 2023). "Since a comparative study measuring serum CK levels between patients with PC and benign pancreatic lesions or normal controls is unavailable, the effect of elevated CKB levels on the serum CK level requires further investigation." (PMID 36653771, 2023). "The CKB expression was positively correlated with tumor purity (Cox = 0.196, p = 1.01e−02) and infiltration of some immune cells, including CD4+ T cells (Cox = 0.161, p = 3.54e−02), MDSC (Cox = 0.227, p = 2.86e−3)." (PMID 35664305, 2022).
tumor (continued). "Tumor cells secrete brain-type creatine kinase (CKB) in response to hypoxia as a mechanism of adaptation to metabolic stress under these conditions." (PMID 36497411, 2022). "CKB was necessary for cell invasion in vitro and strongly promoted tumor growth and lung metastasis in vivo." (PMID 35008190, 2021). "We identified CKB as an HIF-1α-dependent target gene necessary for tumor outgrowth and lung metastasis in the MMTV-PyMT transgenic model of MBC." (PMID 35008190, 2021). "Our analysis of CKB protein expression in human prostate normal and tumor tissue microarrays concords with this observation." (PMID 34706306, 2021). "Remarkably, deletion of this single HIF-1 target gene produced tumors with similar volumes to HIF-1 KO cells, suggesting that tumor-cell-intrinsic CKB directly influences the local surrounding microenvironment to promote tumorigenesis." (PMID 35008190, 2021). "SRC, LYN and CKB immunoreactivity was detected in 72 (52.2%), 66 (47.8%) and 0 (0%) of the tumor samples." (PMID 26460485, 2015). "In contrast, a gradual significant decrease in CKB protein and mRNA expression was observed corresponding to the tumor stage (p < 0.008, for most of the comparisons)." (PMID 26460485, 2015). "The cytosolic CKB is induced in a variety of tumours, including neuroblastoma, small cell lung carcinoma, colon adenocarcinoma, and breast carcinoma." (PMID 20302626, 2010). "Besides tumor-promotion, our results also indicate a possible role of CKB in regulating migration and metastasis of OSA cells." (PMID 41345636, 2025). "CKB‐AKT signaling is involved in the mitochondrial energy metabolism of tumor progression." (PMID 38896801, 2024). "Additionally, our discoveries suggest that CKB's regulation of mitochondrial ATP production is probably conserved in specific types of cancer cells thriving in a murine tumor model and diminishes with aging." (PMID 38896801, 2024). "Notably, the CKB‐AKT signaling axis boosts mitochondrial ATP production in cancer cells growing in a mouse tumor model." (PMID 38896801, 2024). "CKB generates phosphocreatine, which can subsequently be used by tumor cells to obtain ATP." (PMID 36497411, 2022). "Notably, protein extracts were prepared from whole tumors, containing proteins expressed by tumor epithelial cells and the stroma, likely minimizing the total reduction in CKB because only the tumor epithelium lacks HIF-1α." (PMID 35008190, 2021). "For example, local extracellular secretion of CKB by colon cancer cells into the liver microenvironment promotes metastatic outgrowth through the extracellular production of phosphocreatine (PCr), which was then imported into tumor cells as an energy source." (PMID 35008190, 2021). "Moreover, the anti-tumor activity of RGX-202 is directly correlated with CKB expression levels, as we have observed in metastatic breast cancer models." (PMID 35008190, 2021). "CKB was participated in metabolic processes involving glycolysis and could serve as a biomarker for predicting tumor progression." (PMID 33292266, 2020). "SRC, LYN and CKB proteins or DNA methylation could serve as markers for predicting tumor progression and target in anti-cancer strategies." (PMID 26460485, 2015). "Notably, CKB silencing promotes orthotopic xenograft tumor growth and lung metastasis of PC3 cells." (PMID 34706306, 2021). "Importantly, CKB overexpression inhibits subcutaneous (s.c.)xenograft tumor growth of PC3 cells." (PMID 34706306, 2021). "In a colon cancer model, CKB was shown to mediate the metastatic potential of cancer cells by acting as a secreted kinase to produce phosphocreatine, which accumulated in the stroma and was then re-imported into tumor cells to promote CK-dependent survival to facilitate liver colonization." (PMID 35008190, 2021). "Therefore, SRC, LYN and CKB expression or DNA methylation could be useful markers for predicting tumor progression and targeting in anti-cancer strategies." (PMID 26460485, 2015).
tumor (continued). "Tumor-specific deep crypt secretory cells (tDCS, cluster 10) demonstrated elevated expression of TFF1, FABP1, CKB, PRAP1, IL32, GPRC5A, and SOD3, and were consistent with secretory lineage plasticity and immune or stress-associated signaling." (PMID 41282138, 2025). "The modest but significant positive correlations suggest that CKB and PCSK1N expression levels tend to increase in MYCN‐high tumor cells, possibly placing them under MYCN regulatory control or within the same oncogenic program." (PMID 40600620, 2025). "Another Elevated ASCL1 gene, CKB, has upregulated expression in both SCLC and ASCL1-high atypical teratoid/rhabdoid tumours, suggesting an ASCL1 interaction with oncogenic potential across various contexts." (PMID 40257984, 2025). "In particular, the identification of CKB and PCSK1N suggests their potential role in driving tumor progression, making them promising targets for novel treatments in MYCN‐driven NB." (PMID 40600620, 2025). "Activation of creatine kinase B (CKB) was identified to phosphorylate GPX4, preventing ferroptosis and fostering tumor growth in mice." (PMID 39036600, 2024). "When comparing expression of CKB and MTCK between primary tumor and the liver metastasis, their expression was upregulated in the metastatic foci." (PMID 37204253, 2023). "Validation using Western blotting analysis on 13 patients with type I EC at tumour stage 1 and 13 endometria samples confirmed the altered abundance of HBB, CKB, LDHB, and HSPB1." (PMID 37569364, 2023). "A heatmap profiles showed that CTSK, MMP9, CKB, CCL18 and COL6A2 were upregulated in macrophages in tumor tissues." (PMID 36466840, 2022). "The enrichment of CKB and VGF in Wnt signaling, FoxO signaling, and DNA replication pathways highlights their critical roles in DNA repair mechanisms and cellular stress responses, where genomic instability drives tumor progression." (PMID 40600620, 2025). "In addition, fetal-I tumor organoids (hepatic-intermediate) expressed markers related to tumor progression and invasion, including TSPAN8, CKB, UCA1, and FXYD3." (PMID 39567475, 2024). "Given that CAFs are reported to be an important stromal component and are critically involved in tumor progression, we reclustered the CAFs and further categorized them into two main types: inflammatory CAFs (iCAFs; CFD, CKB, and DPT) and myoblastic CAFs (myCAFs; INHBA, SULF1, and COL8A1)." (PMID 36725337, 2023). "The abundance of three proteins was associated with texture features that represented intra-and inter-site tumor heterogeneity, with the strongest negative correlation between the CKB protein and cluster dissimilarity (p = 0.047, τ = 0.326)." (PMID 32253542, 2020). "However, the change in serum CK activity is not necessarily consistent with CK overexpression in the tumor tissue; for example, elevated CKB levels in tumor cytosol and low total serum CK activity were reported in breast cancer patients." (PMID 36653771, 2023). "The non-metabolic role of CKB enhances the durability of GPX4, unveiling an intricate process through which tumor cells encounter ferroptosis." (PMID 39036600, 2024).
cancer (34 papers, 2015 to 2026). A tumor composed of atypical neoplastic, often pleomorphic cells that invade other tissues. "Aberrant expression of CKB has been observed in many cancers, where it has been associated with the regulation of cancer cell metabolism, proliferation, survival, plasticity, and motility." (PMID 41345636, 2025). "Creatine Kinase B (CKB) is associated with cancer and is upregulated in RA." (PMID 33479267, 2021). "Jackson Laboratory Clinical Knowledge Base (JAX CKB) is a knowledgebase that incorporates integrated data related to cancer-associated genomic variants, therapeutic efficacy, and clinical trials for interpretation of genomic data in cancer." (PMID 32117976, 2020). "Although a link between CKB and cancer diseases was proposed many years ago, the underlying molecular mechanism has only been uncovered in the last decade and may differ between cancer types." (PMID 41345636, 2025). "However, CKB's role in other cancer types and its cancer-associated mechanisms, in general, are largely unknown." (PMID 34706306, 2021). "With a 22‐ to 36‐fold increase in cancer tissues, CKB shows strong potential as a non‐invasive early detection marker." (PMID 40927964, 2025). "Recently, a new creatine kinase inhibitor was developed to inhibit CKMT and CKB in cancer treatment." (PMID 39769038, 2024). "Our data also implies that CKB's regulation of mitochondrial ATP generation is involved in cancer progression and aging." (PMID 38896801, 2024). "Previous studies have shown that SLC6A8 inhibition prevents the uptake of phosphocreatine/creatine produced from the extracellular space CKB during cancer cell migration." (PMID 39769038, 2024). "The brain type of creatine kinase (CKB) is upregulated in several cancer cells, including breast cancer cells." (PMID 36275445, 2022). "Since CKB modulates metabolic pathways, such as glycolysis, which plays a critical role in cancer cells, a key mediator of aerobic glycolysis, lactate dehydrogenase (LDH), isoform levels were assessed." (PMID 36275445, 2022). "Previous studies observed that genes such as CA9, CKB and GLIPR2 were strongly associated with the prognosis of cancer." (PMID 36341424, 2022). "CKB is a cytosolic isoform of creatine kinase (brain type) and is upregulated in a variety of cancers." (PMID 33663560, 2021). "We selected CKB for further study as potential repressor of cancer progression because its mRNA expression is significantly downregulated in many solid cancer types compared to normal controls." (PMID 34706306, 2021). "Among them, we chose to focus on CKB (creatine kinase, brain-type), because its downregulation in multiple solid cancer types is strikingly consistent as found in multiple public cancer genomics and proteomics datasets." (PMID 34706306, 2021). "In general, CK is involved in cancerous transformation, as CKB (brain-type CK) is upregulated in a variety of cancers to support growing energy needs." (PMID 32509571, 2020). "Creatine kinase Brain (CKB) in liver metastatic cancer cells is released to the extracellular microenvironment converting ATP and creatine into phosphocreatine, which is imported into cancer cells to counteract hypoxic response." (PMID 26964533, 2016). "Our data place NSCLC among the growing list of cancers regulated by CKB." (PMID 41072771, 2025). "Here, cancer cells may upregulate and release creatine kinase‐B (CKB) into the extracellular space where it generates the high‐energy metabolite phosphocreatine that is transported into the cell by the SLC6A8 transporter protein." (PMID 40903981, 2025). "The specific and critical role of CKB in determining cancer cell sensitivity to F1F0 ATP synthase inhibition suggests that CKB may influence mitochondrial energy metabolism." (PMID 38896801, 2024).
cancer (continued). "Others like bikunin and creatine kinase B (CKB) only predict cancer development." (PMID 38535506, 2024). "Analysis of both Arg2 and CkB genomic loci revealed a reduction of the acetylation of lysine 27 of histone H3 (H3K27ac), a histone marker indicating a permissive status of the chromatin, in cancer tissues as compared to the normal counterpart." (PMID 39587609, 2024). "Several types of cancer cells exhibit upregulated CKB expression, but the function of CKB in cancer cells remains unclear." (PMID 36275445, 2022). "The reason that we studied CKB as a top candidate for EMT negative regulators identified from our cDNA screen is that its downregulation consistently correlates with poor prognosis in several cancers." (PMID 34706306, 2021). "However, in other cancer types, the downregulation of CKB and rewiring of metabolism may play an important role in colon cancer progression." (PMID 32509571, 2020). "Creatine Kinase B (CKB) is a key enzyme in cellular energy balance and has emerged as a promising biomarker in several cancers such as OC." (PMID 40927964, 2025). "Their findings suggest that in stiffer environments, CKB plays a critical role following YAP-mediated transcriptional regulation to drive phosphocreatine synthesis, cancer cell invasion, chemotaxis and metastasis of primary murine PDAC cells and PANC-1 cells." (PMID 39830124, 2024). "As a group of enzymes that directly cause creatine and phosphocreatine transformation and undoubtedly play important roles in cancer promotion, two CKs are believed to be closely connected with oncology: CKMT1 in mitochondria and CKB in the brain." (PMID 39769038, 2024). "In this study, we showed that inhibition of the creatine shuttle by blocking CKB and MTCK activity suppressed the growth, stemness, and metastasis of cancer." (PMID 37204253, 2023). "Therefore, CKB's underexpression may be a poor prognosticator and its C-terminal fragment may become a starting point of developing peptide therapeutics for prostate and other cancer types." (PMID 34706306, 2021). "Since CKB-silenced cells do not show a defect in migration, we next investigated the process of intravasation, where cancer cells must resist anoikis." (PMID 41072771, 2025). "In spite of many datasets showing CKB downregulation in different cancers, the role of CKB in cancer progression has not been extensively studied." (PMID 34706306, 2021). "Additionally, we categorized the 57 cancer cell lines from the Gboxin sensitivity screen into five groups based on their sensitivities, illustrating a positive correlation between the expression of CKMT1A, CKMT1B, and CKB and the cell's sensitivity to Gboxin treatment." (PMID 38896801, 2024). "Interestingly, CKB is overexpressed in most cancer types, but not in CRC." (PMID 31737124, 2019).
infection (6 papers, 2014 to 2023). The state of being infected such as from the introduction of a foreign agent such as serum, vaccine, antigenic substance or organism. "Since we found large effects in infection of the deletion of the CKb components, we decided to investigate localization of GFP-CKa in the appressoria." (PMID 31058100, 2019). "With regard to creatine metabolism, expression of creatine synthesis enzyme genes GATM and GAMT decreased as a result of Mtb infection, while the creatine transporter SLC6A8 and creatine kinase (brain-type, CKB) were increased, most notably in our M2 infection model." (PMID 32341411, 2020). "HSP60, stress induced phosphoprotein, T-complex protein 1 subunit epsilon, Creatine Kinase B, Pyridoxal phosphate phosphatase and ubiquitin carboxyl-terminal hydrolase PGP9.5 showed a consistent decline post infection." (PMID 24599148, 2014).
neurological disorders (4 papers, 2018 to 2023). "Creatine kinase-BB (CK-BB) is an isoenzyme that is found in astrocytes, and it has been reported that the activity of the CK-BB enzyme is significantly increased in infants with neurological disorders." (PMID 38026658, 2023).
neurodegenerative disease (2 papers, 2011 to 2025). A disorder of the central nervous system characterized by gradual and progressive loss of neural tissue and neurologic function. "Potential applications of dietary creatine supplements and approaches that enhance the expression of CKB for degenerative diseases (including HD) with energy deficiency and SNHL warrant further investigations." (PMID 21685512, 2011).
hematologic malignancies (1 paper, 2022). "The mRNA expression level of CKB increases with an unmethylated CKB promoter in hematologic malignancies." (PMID 35664305, 2022).